INS (insulin)
Diseases named in the same sentence as INS in open-access papers (continued):
Sharing a sentence is not in itself a finding about the gene and the disease.
Insulin resistance (continued). "BMI had a significant straight correlation with insulin resistance (p<0.001) and a negative correlation with insulin sensitivity (p<0.001)." (PMID 30197771, 2018). "The results from this study agrees with reports in which insulin increases testosterone synthesis in the absence of insulin resistance." (PMID 29566712, 2018). "This induction of insulin resistance was independent of MG-generated oxidative stress and likely due to direct binding of MG to the important insulin signaling protein, IRS-1." (PMID 30250846, 2018). "Taken together, these studies suggest that the ATX-LPA pathway promotes fibrosis in severe cases of insulin resistance/diabetes (e.g., db/db mice), a mechanism by which ATX-LPA may further exacerbate impaired insulin function." (PMID 29570618, 2018). "Furthermore, we also found that insulin resistance coexisted with mitochondrial dysfunction in patients and cows with NASH, and NEFA treatment impaired the insulin pathway in hepatocytes." (PMID 29602237, 2018). "To examine the role of adipocyte hormones and LPS in reduced insulin sensitivity in HIV patients, in the present study, we investigated the role of adiponectin, leptin, visfatin and LPS plasma levels in the insulin resistance of HIV-infected patients treated with HAART." (PMID 29434676, 2018). "Then, it is reasonable to speculate that IL-13 plays a protective role in insulin resistance by promoting IRS-1 and AKT phosphorylation in insulin-dependent tissues via STAT3 and STAT6 activation as well as improvement of the beta-cell function." (PMID 29675435, 2018). "Insulin resistance (IR) occurs in most T2DM patients and body sensitivity to insulin decreases." (PMID 30356368, 2018). "At steady state, insulin resistance is measured by the index, HOMA-IR (defined as Insulin(IU)." (PMID 30307959, 2018). "Impaired insulin sensitivity is induced by obesity; additionally, higher TNF-α and FFA levels and lower adiponectin levels are identified as major triggers for obesity-induced insulin resistance." (PMID 29718998, 2018). "After omentectomy, plasma leptin, insulin, NPY, AGRP, and PMCH levels decreased, which may result a decrease in leptin and insulin resistance." (PMID 29367725, 2018). "Insulin resistance and lack of insulin secretion due to pancreatic β-cell failure are among the leading causes of type 2 diabetes." (PMID 30533432, 2018). "Recently, in a human study, established to identify pathways related to insulin resistance, the combination of gene expression and metabolomics revealed perturbed BCAA catabolism and fatty acid oxidation in skeletal muscle from insulin-resistant human subjects." (PMID 29751643, 2018). "However, some other studies have reported that ALT levels were associated with NAFLD, obesity, some features of MetS, fasting insulin levels and HOMA-IR as a marker for insulin resistance." (PMID 30892481, 2018). "The increase in insulin levels and, consequently, in Homa-IR during GHT probably does not indicate with any certainty a condition of insulin resistance, probably due to the inability of basal indexes to reliably assess insulin sensitivity." (PMID 29942285, 2018). "Furthermore, these mice exhibited a significant reduction of insulin resistance index (HOMA-IR) and the improvement of glucose tolerance (OGTT) and insulin response (ITT) following Ln4 administration." (PMID 29783731, 2018). "The use of these parameters to calculate the HOMA‐IR metric to quantify insulin resistance suggests that KD fed mice are slightly more insulin sensitive than chow fed mice after 3 days, whereas HFD fed mice show slightly impaired insulin signalling according to HOMA‐IR compared to KD mice." (PMID 30089335, 2018).
Insulin resistance (continued). "Fasting triglycerides and total-cholesterol levels were higher in patients with HIV-lipodystrophy and so were fasting insulin, HOMA-IR and the insulin response during an OGTT when compared to control subjects from both group 1 and 2, indicating insulin resistance in patients with HIV-lipodystrophy." (PMID 29342149, 2018). "To investigate whether mTORC1 signaling mediates CCRK-promoted insulin resistance, we treated LO2-CCRK cells in hyperinsulinemia condition and found that induction of CCRK further impaired insulin sensitivity (lane 6 vs. lane 4)." (PMID 30523261, 2018). "Some studies have reported beneficial effects of probiotics on serum insulin levels and insulin resistance, but they were restricted to T2D individuals and did not consider obese patients." (PMID 29914095, 2018). "Defects in insulin action in skeletal muscle are also noted in non-diabetic first-degree relatives of people with type 2 diabetes, indicating that insulin resistance is an early event in the pathogenesis of type 2 diabetes." (PMID 29022062, 2018). "Several studies have assessed associations between vitamin D and serum indexes of pancreatic β-cell function and insulin resistance that reflect the pathogenesis of T2D, including the quantitative insulin sensitivity check index (QUICKI), fasting insulin, and HbA1c." (PMID 30627160, 2018). "Insulin resistance is the condition where the body fails to respond appropriately to circulating insulin, leading to the impaired systemic glucose clearance and uptake in several tissues including the adipose tissue, liver, and muscle." (PMID 30483273, 2018). "The insulin resistance of puberty, which was found to be directly correlated with IGF-1 levels, leads to compensatory hyperinsulinemia which serves to amplify the anabolic effect of insulin during this period of rapid growth." (PMID 29942285, 2018). "The use of omega 3 to counteract inflammation, oxidative stress and to improve systemic insulin resistance in healthy, insulin resistant and elderly subjects is not likely to provide any benefit." (PMID 29324650, 2018). "Our results demonstrated that yoga intervention did not improve β-cell function and insulin resistance in centrally obese MetS adults, except a tended improvement in insulin sensitivity indicated by HOMA2-%S." (PMID 30294284, 2018). "HOMA-IR has proved to be a robust tool for the assessment of IR as it is a model of the relationship of glucose and insulin, that predicts fasting steady-state glucose and insulin concentrations, while the HOMA-IR and HOMA-%β are indices of hepatic insulin resistance and β-cell function." (PMID 30273360, 2018). "Fasting insulin concentration, Matsuda index, the homeostatic model assessment of insulin resistance (HOMA‐IR), and glucose AUC did not change in either group." (PMID 30156033, 2018). "Individuals with T2DM manifest selective hepatic insulin resistance in which insulin fails to suppress gluconeogenesis but continues to activate lipogenesis, producing the deadly combination of hyperglycemia and hypertriglyceridemia." (PMID 30692925, 2018). "Glucose metabolism was assessed with fasting glucose, glycated hemoglobin (HbA1c), plasma C-peptide and insulin, quantitative insulin check index (QUICKI), and a homeostatic model assessment of insulin resistance (HOMA-IR) and β cell (HOMA-β) before surgery and 6 months after surgery." (PMID 29718860, 2018). "Insulin resistance is defined as a situation in the human organism in which it does not respond sufficiently to the physiological levels of insulin." (PMID 29382127, 2018). "The condition of brain insulin resistance was characterized by reduced levels of insulin and IGFs, no compensatory hyper-expression of their receptors and therefore a reduced transduction pathway." (PMID 30096758, 2018).
Insulin resistance (continued). "As high plasma glucose levels are a component of metabolic syndrome, we evaluated the effect of consuming the WGPF-burger and control-burger on glycemia and plasma insulin, and calculated the HOMA (homeostatic model assessment) index—a reliable and clinically useful indicator of insulin resistance." (PMID 30275350, 2018). "Indices derived from fasting glucose and insulin including homoeostasis model assessment-insulin resistance (HOMA-IR) and quantitative insulin-sensitivity check index (QUICKI) are widely used to quantify insulin resistance." (PMID 30577478, 2018). "Insulin resistance (IR) is an important pathological condition of T2DM, in which the body is still able to produce insulin but the cells become resistant to its effect, making insulin ineffective in regulating blood sugar levels." (PMID 29721029, 2018). "T2DM is a long-term metabolic disorder characterized by high blood sugar, insulin resistance (IR) and relative lack of insulin." (PMID 30298019, 2018). "Insulin resistance is also considered to be a significant pathological characteristic of MS and it has previously been reported that SBP improved insulin resistance as evaluated via glucose tolerance testing (GTT) and insulin dose-response curves." (PMID 29551973, 2018). "Insulin resistance was assessed by HOMA and the insulin response during an OGTT." (PMID 29342149, 2018). "Given the central role of AMPK in insulin action, these data suggest that AMPD may be a new therapeutic target for the attenuation of insulin resistance." (PMID 30336561, 2018). "Nevertheless, ER stress does not seem to play a key role in muscle insulin resistance, because it has been reported that chemical chaperones which reduced ER stress, did not improve palmitate-induced alterations of insulin signalling in myotubes." (PMID 29538286, 2018). "However, serum insulin levels and HOMA-IR index were increased in NPY and DIO-NPY compared to their control groups suggesting insulin resistance." (PMID 29674968, 2018). "On the other hand, when the obese PCOS were compared to the obese control, the significant differences were lost between the two groups in BMI, leptin, ghrelin, insulin, HDL-C and HOMA-S, but the differences persisted in all the lipids, in glucose level and insulin resistance." (PMID 30131073, 2018). "Akt2 is a key to insulin function, as mice lacking Akt2 have insulin resistance and a diabetes mellitus-like syndrome occurred." (PMID 30116147, 2018). "However, the ability of insulin to inhibit lipolysis and reduce the plasma FFA concentration is markedly impaired in insulin resistance." (PMID 29601606, 2018). "Moreover, insulin resistance takes place due to the excessive accumulation of TAG in β-cells, which will exhaust these cells and alter insulin synthesis." (PMID 29805204, 2018). "Insulin resistance was determined according to homeostatic model assessment of insulin resistance (HOMA-IR), and calculated by the following formula: fasting glucose level (mg/dL) × fasting insulin level (mU/mL)/405." (PMID 29764479, 2018). "Despite the loss of early insulin sensitivity, HFO did not develop insulin resistance compared to the CFO, at least up until our final measurement (12 months of age)." (PMID 29484855, 2018). "Studies performed inrodent models of insulin resistance indicated that PPAR-αactivation by natural (FAs) or synthetic (fibrates) ligands,enhances insulin sensitivity by decreasing the lipid contentof adipose and nonadipose tissues or decreasing theendogenous glucose production." (PMID 29308616, 2018). "The Westernization of diets mostly elevate insulin resistance in Asians which that is not compensated due to low insulin secretion capacity." (PMID 30041479, 2018). "The present meta-analysis found that probiotic supplementation resulted in a significant reduction in FBG, insulin resistance, and insulin concentration in pregnant women, especially without GDM diagnosis." (PMID 30388861, 2018).
Insulin resistance (continued). "Based on these findings, it is reasonable to speculate that SOCS3 is involved in the development of insulin resistance in the human body and that increased levels of SOCS3 could lead to pathological conditions that disrupt the insulin signaling pathway." (PMID 29973864, 2018). "The study of FGF21 in individuals with ISO and insulin-resistant overweight and obesity (IRO) can help us to understand whether FGF21 is involved in the protection from the progression to insulin resistance in the development of obesity." (PMID 29348470, 2018). "Most found a relation between either eGFR or the prevalence of CKD with insulin resistance measured by the HOmeostasis Model Assessment of Insulin Resistance (HOMA-IR) or by insulin concentrations, but not always after adjustment for confounders." (PMID 29855339, 2018). "Together, these results indicate that serum UA plays a more important role in augmenting insulin secretion rather than in insulin resistance." (PMID 29568712, 2018). "Many studies indicate that visceral adipose tissue, independent of obesity, is a major determinant of insulin resistance and contributes to variations in insulin sensitivity, even in healthy nonobese subjects." (PMID 29997675, 2018). "In addition, treatment of C2C12 cells with T at 5 × 10-7 M impaired mitochondrial function and reduced insulin-stimulated GLUT4 translocation and glucose uptake, leading to insulin resistance." (PMID 29552281, 2018). "Moreover, we found a significant decrease in fasting insulin among the participants taking vitamin D supplementation especially among those taking a high dose (≥4000 IU/d), which suggests that a high dose of vitamin D supplementation might improve the insulin resistance." (PMID 30627160, 2018). "In type II diabetes patients, the pancreas fails to secrete sufficient insulin or is insulin resistance which leads to postprandial hyperglycaemia." (PMID 29755552, 2018). "Some but not all trials have identified beneficial effects on insulin secretion, glucose homeostasis, and insulin resistance among nondiabetic individuals." (PMID 30627160, 2018). "Therapeutically, the glucose transporter isoform GLUT4 could be a crucial target to treat insulin resistance, since GLUT4 is an insulin-dependent isoform which is responsible for most insulin-stimulated glucose uptake." (PMID 29382104, 2018). "Although insulin levels doubled in hypoxic dams in late pregnancy compared with mid gestation, their insulin resistance score did not change whereas the normoxic dams’ HOMA-IR score increased nearly 3-fold in late- compared with mid-gestation." (PMID 30206264, 2018). "We assessed the insulin resistance by the homeostasis model assessment for insulin resistance (HOMA-IR) in 68 patients without insulin injections." (PMID 29582352, 2018). "Consequently, ZFR showed significantly higher values of the indexes of insulin resistance (HOMA-IR), pancreatic β cell functionality (HOMA-β), and a decreased insulin sensitivity index (QUICKI) when compared to the lean rats." (PMID 29614007, 2018). "Moreover, the ITT showed that the blood glucose levels after insulin injection in the SD- and HFD Y680-fed groups were lower than those in HFD rats (p < 0.05), indicating that yacon improved glucose tolerance and insulin resistance in HFD rats." (PMID 30510798, 2018). "The metabolic behavior of obese individuals who do not have AT insulin resistance is similar to that of lean individuals, with near-normal muscle insulin sensitivity; hence this group of obese individuals usually does not develop NAFLD." (PMID 30011790, 2018). "Female dogs in diestrus or pregnancy can have increased insulin resistance and higher insulin, but we did not include females which had recently been in heat in this study." (PMID 29508262, 2018).
Insulin resistance (continued). "Our results are in accordance with few previous studies that showed significant improvement of insulin sensitivity after anti-TNF therapy in patients with rheumatoid arthritis, psoriasis, and ankylosing spondylitis, especially in subgroups with higher insulin resistance." (PMID 29576769, 2018). "Then the only difference in the functional outcome (LTP) between the Liver-PtenKO mice and the high-fat diet-fed mice can be attributed to the absence of central and brain insulin resistance and the occurrence of a robust insulin signaling pathway." (PMID 30235271, 2018). "Whereas, O-GlcNAcylation of several insulin-signaling key players (such as AKT, PT1B, and PDK1) has been shown to be associated with insulin resistance in the liver, the effect of the HBP on insulin signaling in the heart has not been adequately addressed." (PMID 30420836, 2018). "Similarly, the Matsuda index of insulin sensitivity was lower, and the HOMA index of insulin resistance is higher in GDM." (PMID 29764499, 2018). "These mice also had a 2.5-fold increase in fasting insulin levels indicative of insulin resistance, although this did not quite reach statistical significance due to inter-animal variability." (PMID 29910467, 2018). "Type 2 diabetes is prevented and treated by reducing insulin resistance and increasing insulin capacity in both Asians and non-Asians, although the disease has a somewhat different etiology in Asians than non-Asians." (PMID 30041479, 2018). "Homeostasis model assessment insulin resistance (HOMA-IR) is a validated and commonly used marker of insulin resistance which incorporates both glucose and insulin concentrations and represents insulin resistance that can promote atherosclerosis through several mechanisms." (PMID 29732028, 2018). "Lactobacilli such as Lactobacillus acidophilus (L. acidophilus) have well known properties on prevention of T2D and insulin resistance but not on insulin degradation." (PMID 29751685, 2018). "The HFD treatment paradigm produces a sexually differentiated central insulin resistance, where males but not periovulatory females exhibit a marked diminution in the insulin-induced activation of TRPC channels." (PMID 29973869, 2018). "The ratio showed negative correlations with insulin resistance, TG and the TG/TC ratio and positive correlation with insulin sensitivity in the current study." (PMID 29387323, 2018). "Lipoprotein size, and levels of totalcholesterol (TC), lipoproteins, apolipoprotein AI and B (APO AI/APO B),glucose, insulin, insulin resistance index (HOMA-IR) and non-esterifiedfatty acids (NEFA) were assessed in blood samples." (PMID 29791572, 2018). "This mutual influence and regulation between insulin and ENPP1 seem to further suggest that ENPP1 might contribute to insulin resistance through the down-regulation of insulin action and promoting hepatic gluconeogenesis." (PMID 29513794, 2018). "Muscle is a major factor in peripheral insulin resistance, but the reported microRNAs related to insulin sensitivity in muscle were not reflected in the microRNA changes shown here after only 21 days." (PMID 30687230, 2018). "Type 2 diabetes is a long-term metabolic disorder that is characterized by high blood sugar, insulin resistance, and relative lack of insulin." (PMID 29795313, 2018). "Under the condition of insulin resistance in adipose tissue, insulin is unable to suppress lipolysis, resulting in a lack of FFA suppression after glucose loading." (PMID 29615971, 2018). "In conditions of insulin resistance, the impaired glucose uptake—primarily due to the defective regulation of glucose transporter isoform 4 (GLUT4)—has significant effects on whole body glucose homeostasis and insulin action." (PMID 29538286, 2018).